HIF1A (hypoxia inducible factor 1 subunit alpha)
Diseases named in the same sentence as HIF1A in open-access papers (continued):
Sharing a sentence is not in itself a finding about the gene and the disease.
liver cancer (continued). "In the process of gene therapy, the interference gene can effectively silence HIF-1α expression in liver cancer cells under the condition of hypoxia, so as to effectively restrain the formation of new blood vessels in liver cancer tissue after TAE." (PMID 30911540, 2019). "hnRNPA2B1 plays an important role in the accumulation of HIF-1α in Hep3B liver cancer cells under mimetic hypoxia." (PMID 30755586, 2019). "In this study, HIF-1α shRNA was imported into liver cancer cells in the aid of UTMD and then embolism tumor blood vessels by TAE." (PMID 30911540, 2019). "Liver cancer cells treated with the compound grew slowly and produced less HIF-1α under both normal and low-oxygen culture conditions, highlighting the potential of this anti-cancer strategy." (PMID 30755586, 2019). "There are also some limits in the present study; in the future studies, we will further investigate the role of HIF-1α and Akt in the effects of melittin on liver cancer cells using RNA interference." (PMID 31057657, 2019). "Overexpression of HIF-1α promotes the growth, migration, and invasion of liver cancer cells and induces the upregulation of VEGF, which is one of the most potent angiogenic factors presented in various human cancers." (PMID 31057657, 2019). "Collectively, our results supported the findings that the miR-3662/ HIF-1α axis played a key role in regulating Warburg effect, proliferation process, and cell cycle distribution in liver cancer cells." (PMID 29748591, 2018). "Consistent with the previously reported results in liver cancer cells, miR-338-3p mimics inhibited HIF1α expression in MCF-7 and 4T1 cells, whereas anti-miR-338-3p increased HIF1α expression." (PMID 28703807, 2017). "In this study, the results showed that HIF1α stabilizers increased the uptake of DZ-1 by liver cancer cells, while OATP inhibitors reduced the NIR dye uptake." (PMID 28635650, 2017). "These clinical observations reinforce the cancer-specific targeting ability of NIRF dye as well as the roles of HIF1α/OATPs in mediating dye uptake in liver cancer." (PMID 28635650, 2017). "As the PKM2 gene was shown to be transcriptionally activated by HIF-1a in different cell lines, we checked their protein levels in liver cancer cells." (PMID 27203546, 2016). "Under the effect of miR-199a-3p in liver cancer cells, HIF-1α was found to be involved in cellular proliferation and cancer growth." (PMID 22942713, 2012). "Furthermore, several experiments—including scratch assays, tube formation assays, cell permeability assays, and cell viability assessments—were conducted to explore the effects of TCF12 and HIF-1α on vascularization and drug sensitivity in liver cancer." (PMID 40190273, 2025). "Additionally, we performed cell-based functional assays to examine the effects of TCF12 and HIF-1α on migration, tube formation, permeability, and other phenotypic characteristics of liver cancer ECs." (PMID 40190273, 2025). "Studies in liver cancer have shown that elevated hypoxia-inducible factor-1α (HIF-1α) levels after TACE can promote angiogenesis, which may facilitate tumor metastasis/recurrence and potentially induce radioresistance." (PMID 41479799, 2025). "Indeed, the anti-HIF-1α effect of kaempferol, at concentrations close to those achievable with diet, is sufficiently strong to be cytotoxic to liver cancer cells grown in hypoxic conditions." (PMID 39728749, 2024). "In addition, USP22 stabilises HIF‐1α through deubiquitination, and its expression promotes hypoxia and stem cell induced glycolysis in liver cancer cells." (PMID 39661501, 2024). "The formation of such ECM is due to the characteristics of the liver cancer itself, and secondary hypoxia due to the blockade of the arteries supplying the liver cancer by the TACE treatment, which enhances the expression of HIF-1α and causes fibrotic changes in the ECM." (PMID 38955827, 2024).
liver cancer (continued). "Consequently, suppressing the expression of HIF-1α protein through RLX administration effectively inhibited the metastasis of the remaining liver cancer." (PMID 38955827, 2024). "However, our focus on the hypoxic tumor microenvironment in liver cancer has led us to believe that the influence of BCLAF1 extends beyond the regulation of HIF-1α transcription during normoxic states." (PMID 37906282, 2023). "Finally, a recent study also reported that ubiquitin specific peptidase 2 antisense RNA 1 (USP2-AS1) overexpression under hypoxia diminished lenvatinib efficacy by increasing HIF-1α expression in liver cancer." (PMID 36376373, 2023). "In addition, the glycolysis intensity was significantly correlated with the expression of PD-L1 in CD86+ macrophages in liver cancer and the mechanism involves HIF-1α-dependent elevation of PKM2." (PMID 37434177, 2023). "Importantly, RPLP2 regulates aerobic glycolysis and liver cancer cell proliferation via TLR4-mediated HIF-1α translocation into the nucleus." (PMID 38052785, 2023). "Given the evidence, we speculated that NECAB3 might regulate liver cancer progression via modulating the HIF-1α/RIT1 axis." (PMID 37215053, 2023). "Furthermore, in liver cancer, HIF-1α has been shown to modulate cancer growth and metastasis and cell sensitivity to Sorafenib through inducing Ras like without CAAX 1 (RIT1) expression." (PMID 37215053, 2023). "Protein crotonylation level positively correlates to HIF1α expression in liver cancer." (PMID 35977926, 2022). "HIF1A upregulates TM4SF1-AS1 expression to enhance the migration of liver cancer cells." (PMID 36230902, 2022). "Conversely, BBR can inhibit the expression of HIF-1α as a synergistic treatment for liver cancer." (PMID 35153781, 2022). "LncRNA ZFPM2-AS1 enhances the migration of liver cancer cells by upregulating HIF1A." (PMID 36230902, 2022). "Our findings also suggest that USP2-AS1 could increase the protein level of HIF1α by enhancing YBX1 protein binding to HIF1α mRNA under hypoxia and the therapeutic effect of lenvatinib can be enhanced by combination with HIF1α inhibitors in liver cancer." (PMID 35692750, 2022). "Circ-0046600 knockdown suppresses the migration of liver cancer cells by upregulating HIF1A." (PMID 36230902, 2022). "More importantly, our data suggest that the development of a SOCS5-specific inhibitor, an indirect inhibitor of HIF-1α, may be effective in controlling Pringle maneuver-induced tumor micrometastases during liver cancer resection." (PMID 36319626, 2022). "The overexpression of TRPC6 causes a continuous increase in intracellular free calcium and regulates the EMT, HIF1-α signaling, and DNA damage repair mechanisms related to multidrug resistance to stimulate and enhance the resistance of liver cancer cells to multiple drugs." (PMID 36187789, 2022). "Therefore, the therapeutic effect of sorafenib is increased in liver cancer when it is combined with HIF1α inhibitors." (PMID 35692750, 2022). "This indicates that the combination of ASP and HIF-1α RNAi for the treatment of liver cancer may act by inhibiting angiogenesis through the PI3K and MAPK signaling pathways." (PMID 34335854, 2021). "Moreover, in the process of liver cancer metastasis, HIF-1α regulates zinc finger transcription factors to affect the expression of EMT markers, such as E-cadherin, N-cadherin, and vimentin, and promotes invasion and metastasis." (PMID 34335854, 2021). "However, there is no research evaluating the relationship between MOF expression and HIF-1α expression in liver cancer." (PMID 34540836, 2021). "Hypoxia-induced factor 1α (HIF-1α) is the primary factor in liver cancer hypoxia." (PMID 33995620, 2021).
liver cancer (continued). "As hypoxia induced upregulation of Fascin-1 in liver cancer cells, we speculated that the HIF-1α signaling might regulate Fasin-1 expression to some extent." (PMID 34897283, 2021). "ELK3 elevates the expression of HIF-1α and promotes the migration of liver cancer stem cells." (PMID 34917613, 2021). "This study aimed to demonstrate that ginsenoside compound K (20 (S)-ginsenoside CK; CK) downregulates Bcl-2-associated transcription factor 1 (Bclaf1), which inhibits the hypoxia-inducible factor-1α (HIF-1α)-mediated glycolysis pathway to inhibit the proliferation of liver cancer cells." (PMID 33363466, 2020). "We thus investigated whether CK could inhibit the expression of HIF-1α through Bclaf1 and thus affect the glycolysis pathway of liver cancer cells." (PMID 33363466, 2020). "In order to investigate whether CK could inhibit the expression of Bclaf1 and the binding of Bclaf1 to HIF-1α, we first observed the expression of Bclaf1 in human liver cancer tissues." (PMID 33363466, 2020). "In order to determine the role of Bclaf1 in the inhibition of liver cancer cell proliferation by CK, we knocked out Bclaf1 and found that it enhanced the ability of CK to activate HIF-1α ubiquitination and inhibit the HIF-1α-mediated glycolysis pathway to inhibit proliferation." (PMID 33363466, 2020). "Lai and colleagues confirmed that LPS could participate in the maintenance of stemness of liver cancer cells by activating NF-κB/HIF-1α signaling pathway." (PMID 32014008, 2020). "In conclusion, this study indicates melittin may inhibit hypoxia-induced VM formation and EMT in liver cancer through inhibiting HIF-1α/Akt pathway." (PMID 31057657, 2019). "By directly targeting HIF-1α, miR-3662 suppressed liver cancer cell glycolysis and proliferation." (PMID 29748591, 2018). "Moreover, we also investigated the expression of HIF-1α protein in tumor tissue of nude mice with a liver cancer xenograft model." (PMID 29348766, 2017). "It was showed that MFB-AC could down-regulate the expressions of extracellular VEGF and intracellular hypoxia-inducible factor-1 alpha (HIF1-α) in CSCs of hepatic cancer." (PMID 27338343, 2016). "Thus, HIF-1α protein has the potential to be an important reference index for estimating the recurrence, metastasis and prognosis of patients with liver cancer." (PMID 25013467, 2014). "Therefore, we inferred that the upregulated NECAB3 might regulate liver cancer progression via modulating the HIF-1α/RIT1 axis." (PMID 37215053, 2023). "Therefore, the high expression of HIF-1α in the development of liver cancer is influenced by AMPK." (PMID 36937390, 2023). "Clinical studies have demonstrated a significant positive correlation between serum copper levels and HIF-1α levels in patients with liver cancer, suggesting that copper accumulation may lead to the activation of HIF-1α and promote the development of liver cancer." (PMID 37427098, 2023). "In addition to the effect on drug resistance of liver cancer cells, other studies have also reported that USP22 can significantly affect the glycolysis and stemness characteristics of liver cancer cells under hypoxic conditions: HIF-1α knockdown inhibits USP22-induced and hypoxia-induced effects." (PMID 35875077, 2022). "Based on these function assays, we assume that HIF1A can regulate the immune regulation, apoptosis, and inflammatory process of liver cancer cells, and it plays an important role in regulating the energy metabolism of liver cancer cells, such as fatty acids, sterols, and carbohydrates." (PMID 35774500, 2022). "Therefore, abnormal upregulation of IGF1R and HIF1A could promote the occurrence and metastasis of HBV-associated liver cancer." (PMID 33863948, 2021).
liver cancer (continued). "Therefore, we further explored whether CK could have an effect on the glycolysis of hypoxic liver cancer cells by regulating HIF-1α activity." (PMID 33363466, 2020). "However, some literature pointed out that Bclaf1 promotes the transcription of HIF-1α in hypoxic liver cancer cells through the bZIP domain, thereby increasing the transcription of downstream targeting factors of HIF-1α and promoting the proliferation of HCC cells." (PMID 33363466, 2020). "Therefore, we speculate that the inhibition of liver cancer cell proliferation by CK may involve regulation of Bclaf1, which in turn inhibits the HIF-1α-mediated glycolysis pathway." (PMID 33363466, 2020). "In addition, overexpression of HIF-1α has been shown to induce EMT of liver cancer." (PMID 31057657, 2019). "In addition, the acetylation/deacetylation of HIF‐1a by HBx may be a critical mechanism of HIF‐1a stabilization to facilitate liver cancer metastasis." (PMID 29316268, 2018). "To investigate the effects of TCF12 and HIF-1α on tube formation and drug sensitivity in liver cancer vascular ECs, we examined three groups: a control group, a TCF12 shRNA group, and a TCF12 shRNA plus HIF-1α group." (PMID 40190273, 2025). "MYB- and HIF1α-co-regulated direct target, KRT19, exhibits positive correlation with HIF1α under hypoxia, while another target, ALDOA is shown to support hypoxic survival of liver cancer cells." (PMID 40680814, 2025). "To understand how Liensinine regulates HIF-1α and AMPK signaling, we analyzed the expression and activation levels of HIF-1α and AMPK in liver cancer cells through Western blotting." (PMID 40665352, 2025). "Research has shown that under hypoxic conditions, HIF-1α transcriptionally activates the VEGF A VEGFA gene, promoting blood vessel formation in liver cancer." (PMID 40190273, 2025). "Hydroxyproline metabolism, as one of the important metabolic processes in cells, has been found to accumulate hydroxyproline in liver cancer, which can promote HCC tumour progression and sorafenib resistance by regulating HIF1α." (PMID 40100076, 2025). "Research on the liver cancer signaling pathway has revealed that bone morphogenetic protein 9 (BMP9) and inhibitor of DNA binding 1 (ID1) can activate the expression of HIF-1α and VEGFA, which affects the angiogenesis of liver cancer lesions." (PMID 39619441, 2024). "In a HIF-1α-dependent manner, the key glycosylase PKM2, induced by liver cancer cell-derived fibrin 1, simultaneously regulates the antitumor properties of glycosylated macrophages and inflammation-mediated PD-L1 expression." (PMID 39070142, 2024). "Recent studies have shown that EVs can alter glycolysis in various tumor cells by targeting HIF-1α, including EVs with ZFPM2-AS1 in liver cancer, EVs with miR-29a-3p in glioma, and EVs with circSHKBP1 in non-small cell lung cancer." (PMID 39434182, 2024). "Some studies have found that BMP9-ID1 can activate the expression of HIF-1α and VEGFA in the blood supply of liver cancer, which provides a new strategy for targeted liver cancer therapies." (PMID 39619441, 2024). "Knockdown of NECAB3 suppressed the aggressive phenotype of liver cancer via modulating the HIF-1α/RIT1 axis, providing a possible target for liver cancer therapy." (PMID 37215053, 2023). "Knockdown of NECAB3 suppressed aggressive phenotype of liver cancer via modulating the HIF-1α/RIT1 axis, providing a possible target for liver cancer therapy." (PMID 37215053, 2023). "In this research, we found that silence of NECAB3 suppressed the HIF-1α expression in liver cancer cells and overexpression of NECAB3 increased HIF-1α expression." (PMID 37215053, 2023). "The expression of HIF1A and NRF2 was highly correlated in liver cancer samples from the TCGA cohort." (PMID 35912211, 2022). "As a crucial regulator involving in the interaction between CAFs and liver cancer cells, CCL5 promotes HCC metastasis through activation of HIF1α/ZEB1 signaling axis." (PMID 35589690, 2022).
liver cancer (continued). "The co-expression analysis revealed that LINC00839 expression levels exhibited a positive correlation with HIF1A expression levels and remarkably, LINC00839 further overexpression was also observed in liver cancer cells cultured under hypoxia." (PMID 36335129, 2022). "In liver cancer, PROX1 can increase the stability of the transcription factor hypoxia-inducible factor 1α (HIF1α) by recruiting histone deacetylase (HDAC1), leading to EMT of liver cancer cells." (PMID 35342346, 2022). "CCL5 inhibited the ubiquitination degradation of HIF1α and up-regulated the downstream ZEB1 to promote liver cancer metastasis." (PMID 35589690, 2022). "We were surprised to find that some studies have shown that in the hypoxic environment of liver cancer cells, hypoxia-induced HIF-1a promotes STIM1 expression and SOCE in liver cancer cells by directly binding to the STIM1 promoter." (PMID 36187789, 2022). "At the human liver cancer sample level, we found that ALKBH5 was significantly related to the expression of HIF-1α, a key marker of hypoxia at the protein and mRNA levels, by investigating the Timer and CPATAC databases." (PMID 35982895, 2022). "Studies on miR-424 showed that it is associated with therapeutic targets for a variety of diseases, such as muscular dystrophy, liver cancer, HPV, and vascular remodeling as well as regulating the STAT, NOTCH, and HIF1A signaling pathways." (PMID 34336976, 2021). "Of note, verteporfin has been shown to inhibit HIF-1α DNA-binding ability and HIF-1α-YAP-binding capacity in a liver cancer model." (PMID 33414428, 2021). "Curcumol inhibited the expression of PD-L1 by overlapping the HIF-1α and p-STAT3 (T705) signaling pathways in liver cancer." (PMID 34884892, 2021). "In summary we found that Hif1-α, VEGF and Akt previously overexpressed in Liver Cancer, were downregulated by taxifolin." (PMID 34113483, 2021). "In the context of liver cancer, SAHA has been shown to inhibit HIF-1α expression and nuclear translocation." (PMID 32793237, 2020). "It was observed that hypoxia inducible factor (HIF) 1α expression is positively correlated with VEGF expression, and the upregulation of HIF1α and VEGF often implies poor prognosis in liver cancer." (PMID 33262947, 2020). "Several studies evidenced the involvement of HIF1α in the regulation of MDR1 gene expression in various tumors, including colon and liver cancer." (PMID 32545695, 2020). "In this study we tried to explore the antitumor effect through a combination of UTMD-mediated HIF-1α shRNA transfection and TAE on rats with hepatic cancer." (PMID 30911540, 2019). "Western blotting and immunohistochemistry were applied to measure the protein level of HIF-1α and VEGF in the hepatic cancer tissue." (PMID 30911540, 2019). "Similar to liver cancer, IL-1β induced EMT in PDAC cell lines accompanied by COX-2 and HIF-1α overexpression." (PMID 31588122, 2019). "Our findings uncover a mechanistic role for miR-3662/HIF-1α axis in HCC metabolic reprogramming, providing a potential therapeutic strategy in liver cancer." (PMID 29748591, 2018). "Pathways for hypoxia-inducible factor (HIF)-1α, VEGF, RNA-binding factor 1(AUF-1), and astrocyte elevated gene-1 (AEG-1) play roles in the progression of liver cancer." (PMID 30524272, 2018). "Previously, we confirmed that the interaction between hif-1α and β-catenin facilitated hif-1α-mediated EMT in liver cancer." (PMID 28705232, 2017).